CDK1 (cyclin dependent kinase 1)
Diseases named in the same sentence as CDK1 in open-access papers (continued):
Sharing a sentence is not in itself a finding about the gene and the disease.
cancer (continued). "Matrine arrests the cell cycle and induces apoptosis in several cancer cell lines, and the mechanism is downregulated cell cycle-related proteins CDK1, Cyclin B1 and Cyclin D1." (PMID 34809653, 2021). "qRT-PCR was used to examine the mRNA levels of some cancer markers such as cell cycle marker (CDK1), epithelial marker (E-cadherin), and mesenchymal marker (vimentin) in Caco-2 cells treated with SE and ZnO SE." (PMID 34976976, 2021). "The results were further validated in the GTEX database; the correlation between HSP90AA1 and BRCA1 and CDK1 was only observed in cancer patients." (PMID 35095481, 2021). "CDK1 is a member of cyclin-dependent protein kinases (CDKs), which was mentioned in the pathogenesis and recurrence mechanism of various malignant tumors." (PMID 33765954, 2021). "A variety of CDK1 inhibitors have been developed, and some have entered clinical trials for cancer treatment." (PMID 34249720, 2021). "Among the several selected DEGs, CDK1 was found to be overexpressed in tumor tissues, compared with para-carcinoma tissues by IHC analysis." (PMID 34032605, 2021). "In cancer biology, CDK1 is overexpressed and the inhibition of CDK1 is considered as a potential therapeutic approach for cancer treatment." (PMID 32414422, 2020). "Here, we report a link between CDK1 and phosphorylation of hTERT at T249, and the phosphorylation occurs more frequently in aggressive and advanced cancers in clinical samples, suggesting an additional role for CDK1 in cancer progression." (PMID 32214089, 2020). "Nocodazole, a prototypic microtubule inhibitor, can cause G2/M cell cycle arrest and results in strong up-regulation of cyclin B1 and CDK1 levels in human cancer cells." (PMID 32181475, 2020). "The combinatorial inhibition of CDK1 and BRD4 has the potential to overcome the low specificity of CDK1 inhibitor as well as cancer resistance to BETi, allowing more effective killing of BRD4-driven cancer cells." (PMID 32575711, 2020). "Knockdown of CDK1 allowed cancer cells to undergo active mitosis and inhibited their sensitivity to all-trans retinoic acid-induced cell cycle arrest in AML cells." (PMID 32596342, 2020). "The optimal model for detecting favorable outcome of disease was determined as the combination of low expressions for Securin (< 10% of cancer cells), Separase (< 1% of cancer cells) and Cdk1 (< 10% of cancer cells)." (PMID 32546141, 2020). "In fact, because cancer cells usually promote CDK1 activity, this property can be useful for targeted cancer therapy." (PMID 32355263, 2020). "Description of the broader role of CDK1 will provide a new insight into the specialized translation and translational control in human diseases such as cancer." (PMID 32605021, 2020). "Based on this finding, it will be interesting to investigate how aberrant CDK1 activation in cancer cells can be explored as a therapeutic target for treating BRD4-associated cancers." (PMID 32575711, 2020). "In HT-29 cancer cells, mechanistically, both OAT-449 and vincristine are associated with the classical signaling scenario of activation of Cdk1, NuMa, Histone H3 and Aurora B, promoting cell cycle progression." (PMID 32759730, 2020). "Minor progress has been made via high-throughput drug screens in several tumors including cyclin-dependent kinase 1/2 (CDK1/2)-, polo-like kinase 1 (PLK1)-, and WEE1-mutated cancers." (PMID 32883316, 2020). "G2/M is the last checkpoint before mitosis which is preferred in cancer cells to repair DNA damage and is regulated by the status of cyclin-dependent kinase 1(CDK1)/cyclin B1 complex." (PMID 33072782, 2020). "CDK1 orchestrates the transition from the G2 phase into mitosis, and as cancer cells often display enhanced CDK1 activity, it has been proposed as a tumor-specific anticancer target." (PMID 33178836, 2020). "Our study thus identifies CDK1 inhibition as a novel strategy to overcome BETi resistance in cancer." (PMID 32575711, 2020).
cancer (continued). "As a representative analysis, a survival plot was generated for the liver and cervical cancer patients with a high and low CDK1 expression, respectively." (PMID 33193699, 2020). "To date, several Wee1 inhibitors have been investigated, some of which are concomitant CDK1 inhibitors, suggesting that Weel is an effective target for sensitizing various types of cancers to radiotherapy." (PMID 32355263, 2020). "Errors in the regulation mechanism of CDK1 directly lead to cell differentiation disorders, cell cycle disorders, malignant cell proliferation and abnormal transformation, and ultimately malignant tumor formation." (PMID 32546690, 2020). "In fact, regulation of the cell cycle in cancer cells is complex, and CDK1 can be upregulated or downregulated by multiple cell cycle checkpoint proteins." (PMID 32355263, 2020). "In connection with this, LARP1 as a substrate of CDK1 is upregulated in certain cancer types, which leads to an elevated survival rate probably via aberrant translation." (PMID 32605021, 2020). "Previous studies also showed that CDK1 expression was upregulated in a majority of tumor tissues, which correlated with the prognosis of cancer patients." (PMID 33200655, 2020). "Knocking out Sox2 in CDK1-overexpressed cells can significantly inhibit CDK1; hence, the CDK1-Sox2 interaction is a potential therapeutic target in cancer." (PMID 32964032, 2020). "Dysregulation of CDK1, which leads to increased cell proliferation, has been identified in various cancers." (PMID 32605021, 2020). "Our study therefore suggests that CDK1 inhibition can be employed to overcome tumor BETi resistance and improve treatments for BRD4-associated cancers." (PMID 32575711, 2020). "For example, after stable transfection or addition to the medium, ZAG inhibits the progression of cancer cells through the cell cycle by downregulation of the cyclin-dependent kinase 1 (CDK1) gene." (PMID 32315567, 2020). "Previous studies have shown that downregulation of cyclin B1 specifically suppresses the activity of Cdk1 further leading to a strong proliferation inhibition and apoptosis induction in various cancer cells, both in vitro and in vivo." (PMID 31803360, 2019). "A previous report has shown that CDK1 is indispensable for survival of cancer cells overexpressing MYC." (PMID 31080551, 2019). "CDK7 is considered as an attractive target for treating human cancer, as it controls the activity of key enzymes involved in cell cycle progression, including other cyclin-dependent kinases such as CDK1, CDK2, CDK4, and CDK6." (PMID 31076643, 2019). "Accumulating studies have demonstrated that several cell cycle–related genes such as CCNB1, CCNA2, and CDK1, which were also identified in the current study, are involved in the initiation and development of cancer." (PMID 31428132, 2019). "It is well known that CCNB1 triggers mitosis in the G2 phase to promote cell proliferation and tumorigenesis by phosphorylation and inhibition of FOXO1 in cancers after binding to CDK1 and initiating the kinase activity 17-19." (PMID 31592235, 2019). "MTT proliferation assay showed that inhibition of CDK1 suppressed cancer cell proliferation as well as invasion, in a time-dependent manner." (PMID 31375708, 2019). "As the DNA damage response (DDR) is suppressed by elevated CDK1 activity, triggering premature mitotic events in combination with DNA-damaging agents has become an attractive therapeutic strategy for cancer patients." (PMID 30190546, 2019). "Cyclin B1, the regulatory subunit of cyclin-dependent kinase 1 (Cdk1), is another interesting target, as it is overexpressed in several cancer cells and plays a role in cancer cell survival and proliferation." (PMID 30866424, 2019). "Our recent study sheds light on this field by elucidating a novel mechanism of CDK1 contributing to cancer stemness." (PMID 31080551, 2019). "As for the relationship between anticancer drugs and hub genes, we found CCNB1 and CDK1 were the targets of cancer drugs." (PMID 31134129, 2019).
cancer (continued). "To date, there are several methods to treat PTX-resistant cancers, such as treatment with microtubule-targeting agents, CDK1, autophagy inhibitors, or apoptosis modulators, or by reducing the drug efflux." (PMID 31259152, 2019). "Iron directly binds CDK1, which is upregulated in several cancers, thereby promoting JAK1 phosphorylation and activation of STAT3 signaling to promote colorectal carcinogenesis." (PMID 30931929, 2019). "In the cell cycle pathway, GSK3B, CDK2, and CDK1 are reduced by cisplatin in each cell line, and in cancer pathways, cisplatin reduces phosphorylation of GSK3B, AKT1, PDGFRa/b, PLCG1/2, and CDK2." (PMID 31929796, 2019). "In epithelial ovarian cancer, upregulated expression of CDK1 has been observed in cancer cells and promotes cancer growth and has a significant effect on the overall survival of patients." (PMID 31886163, 2019). "As expected, overexpression of CDK1, as well as high expression of its binding partner cyclin B1, has been described in many cancers with poor prognosis." (PMID 30190546, 2019). "Dysregulation of the cell cycle checkpoint proteins, such as cyclinB1, cyclin D1, cyclin-dependent kinase 1 (CDK1), CDK4 and CDK6, is a key hallmark of cancer, generating uncontrolled cellular growth and tumorigenesis." (PMID 30700698, 2019). "Many quinonoid-based Cdc25 inhibitors have been identified and demonstrated to inhibit proliferation of cancer cells in a manner similar to CDK1/2 inhibitors." (PMID 30135856, 2018). "The products of hub PCGs mainly function as protein binding molecule and were involved in important biological processes and signaling pathways in cancer (CDK1, MKI67, CENPF, COL4A6, DACH1, etc.)." (PMID 30026672, 2018). "To further investigate the molecular mechanism responsible for the disassembly of lamin A/C in Nestin-knockdown cancer cells, we treated Nestin-knockdown and control cells with inhibitors of Cdk1/2/5 and Akt, respectively." (PMID 30190500, 2018). "CDK1 promotes cell proliferation and survival and it is frequently overexpressed in cancer specimens." (PMID 29843367, 2018). "CDK1 overexpression has been documented in various kinds of human cancers, and was found to be correlated with rapid progression of tumor." (PMID 29903985, 2018). "In particular, the four overlap non-cancer genes (CDK1, CDK2, PLK1 and WEE1), which were validated by the three data resources, were all known anticancer drug targets and clinical trial targets." (PMID 29855504, 2018). "Ro-3306 is CDK1-specific inhibitor that arrests cell cycle at the G2 to M transition and induces apoptosis in cancer cells with prolonged exposure." (PMID 30135856, 2018). "CDK1 gene is known to be a key regulator of the cell cycle pathway, and it is a potential therapeutic target for inhibitors in cancer treatment." (PMID 30514202, 2018). "Disappearance of indirect connections between STIL and CDK1 can be interpreted as loosening the control over several important cyclins (CCNA2 and CCNE1) and the key cell cycle protein CDK1 in cancer." (PMID 29370181, 2018). "The activity of CDK1 is reported to increase aberrantly as cancer cells acquire resistance to paclitaxel." (PMID 29416675, 2018). "The expressions of Cyclin B1 and CDK1 displayed dramatically decreased levels in these cancer cell lines treated with Spiclomazine." (PMID 29467941, 2018). "Taken together, our data suggest that increased sensitivity of CEP55‐knockdown cancer cells to anti‐mitotic agents can be explained by faster entry into mitosis due to premature activation of CDK1." (PMID 30108112, 2018). "Roscovitine (Seliciclib) is one of the first CDK1/2 inhibitors identified and widely demonstrated to sensitize various cancers to DNA damaging agents and radiation." (PMID 30135856, 2018).
cancer (continued). "Treating PTX-resistant cancers has been studied using microtubule-targeting agents, CDK1, histone deacetylase (HDAC) or autophagy inhibitor, or apoptosis modulators, or by reducing drug efflux." (PMID 29374144, 2018). "The top five upregulated DEGs, including CDK1, CCNB1, TOP2A, MYC, and PCNA, were associated with cell mitosis and involved in the development of cancer." (PMID 30092828, 2018). "It has been evident that Cdk1, which is overexpressed and have enhanced kinase activity in many tumor types, is the potential targets for cancer therapy." (PMID 29250124, 2017). "In fact, agents targeting CDK1 or cyclin B have been shown to effectively block tumor growth and progression of multiple forms of cancer." (PMID 29228549, 2017). "Thus, targeting CDK1 to efficiently suppress its expression could induce cell cycle arrest at the G2-M phase, thus to prevent the mitosis of cancer cell, finally cause increased apoptosis of cancer cell." (PMID 29069733, 2017). "The mitotic kinase Cdk1/Cyclin B1 is involved in regulation of G2/M transition and their overexpression is predictive of poor survival and chemoresistance in human cancers." (PMID 29245943, 2017). "We observed that CDK1 inhibition sensitized cancer cells to different genotoxic agents, including aphidicolin and cisplatin." (PMID 29207595, 2017). "Nonetheless, each of these screens identified multiple mitotic kinases as essential in various cancer cell lines, including Aurora B, BubR1, CDK1, and Plk1." (PMID 28337968, 2017). "Since CDK1 is required for mitosis, approaches to target the CDK1-cyclin B complex are appealing for cancer therapy." (PMID 29228549, 2017). "For example, the EGFR mutation and CDK1-mediated kinase activities contribute to USP24 downregulation, resulting in cancer formation by affecting its substrates." (PMID 27991932, 2017). "In this scenario, CDK1 inhibitors with better specificity and pharmacokinetic properties seem to be a promising avenue to pursue cancer treatment." (PMID 29207595, 2017). "Consistent with this pivotal function of CDK1, cancer cells displayed hypersensitivity to a range of DNA damaging agents when CDK1 activity was inhibited." (PMID 29207595, 2017). "Based on our finding that CDK1 is essential for promoting DNA replication fork progression, we explored the possible therapeutic relevance of CDK1 inhibitors in combination with other chemotherapeutic agents in cancer treatment." (PMID 29207595, 2017). "Cytoplasmic CDK1 overexpression was correlated with cancer growth and poor overall survival in 249 EOCs." (PMID 28562334, 2017). "Upregulation of Cyclin dependent kinase 1 (CDK1) protein is closely related with the prognosis of several malignant tumors." (PMID 28899430, 2017). "For example, a selective CDK1 inhibitor, RO-3306, induces cell cycle arrest and apoptosis in cancer cells but has minimal effects on normal cells." (PMID 28434945, 2017). "A similar expression pattern of miR-582-5p was observed in liver tumors and contributes to cancer progression by targeting the cyclin-dependent kinase 1 and AKT serine/threonine kinase 3 genes." (PMID 29207642, 2017). "Cdk1 controls cell cycle entry from G2 to the M phase and is considered as a new anti-cancer drugs target." (PMID 28197098, 2017). "Because CDK1 overexpression is often seen in human diseases such as cancer, a better understanding of its functions will be of great therapeutic relevance." (PMID 29207595, 2017). "Cdk1, which is overexpressed and has enhanced kinase activity in many tumor types, is a potential target for cancer therapy." (PMID 28197098, 2017). "When the normal tissue and cancer tissue groups were compared, cytoplasmic Cdk1 expression in the cancer tissue group was 3.44-fold than that in the normal tissue group." (PMID 27385216, 2016). "In samples derived from the other non-cancer samples, the trace amounts of CDK1 protein were observed." (PMID 26912061, 2016).
cancer (continued). "Trace amount of CDK1 protein was detected in five of the non-cancer larynx tissue samples (i.e., K6, K12, K13, and K14 and total larynx tissue lysate)." (PMID 26912061, 2016). "Several synthetic lethality screens have been performed on KRAS mutant cancer cell lines to determine potential targets, and results have frequently included genes important in cell cycle progression or mitosis, such as CDK1, cyclin A2, PLK1, and CDC6." (PMID 27167191, 2016). "This study not only provides a novel kinase of TAZ, it also suggests that Cdk1-TAZ signaling plays a crucial role in anti-tubulin drug resistance in cancer cells." (PMID 27412635, 2016). "Nevertheless, inhibition by small molecules inhibiting Cdk5 and additionally Cdk1, Cdk2, Cdk7, and Cdk9 have shown promising effects in cancer/angiogenesis." (PMID 26755662, 2016). "These include some known cancer biomarkers such as PCGs CDK1 and TGFBR3, as well lncRNAs PVT1 and ADAMTS9-AS2." (PMID 26812883, 2016). "Cyclin dependent kinase 1 (Cdk1) have previously reported correlation with cancer growth and a key regulator for cell cycle." (PMID 27385216, 2016). "Compared with the normal tissues, the acrophases of Per2 and CDK1 were earlier in precancerous lesions, and the acrophases of Cyclin D1, CDK1 and Cyclin B1 occurred later in the cancer cells." (PMID 25950458, 2015). "Some studies report that, over expression of C53 overrides the G2/M DNA damage checkpoint to promote Cdk1 activation, thereby sensitizing cancer cells to various DNA damage agents." (PMID 26308848, 2015). "8-Hydroxypiperidinemethyl-baicalein (BA-j) is a novel selective CDK1 inhibitor with broad spectrum anti-cancer activity (IC50 12.3 μM) and 2 tumor xenografts." (PMID 26330167, 2015). "Strategies aimed at targeting CDK1 and cyclin B have been proposed and effectively shown to block growth of cancer cells and tumours." (PMID 25625291, 2015). "A number of cellular proteins, including Aurora kinase A, Plk1, Chk1, Chk2, Cyclin B1, and Cdk1, regulate centrosome duplication and the abnormal upstream regulation of these proteins is found in various cancers." (PMID 25999914, 2015). "This study provides opportunities for future research for the role of miR-7 in complementing current therapeutics, combination miRNA therapy and further study of the possible role of miR-7 regulation of CDK1 in cancer." (PMID 26452132, 2015). "Cancer cells use CDK1 and PP2A to regulate the movement of Sp1 in and out of the chromosomes during the cell cycle." (PMID 25398907, 2014). "And the p27 were supposed to have more stable interaction to the CDK1 to work as an inhibitor for sinonasal IPs with cancerization." (PMID 25013792, 2014). "In the present study PPP treatment resulted in prominent CDK1 activation with increased levels of Cyclin B1 protein and mRNA, increased Cyclin B1 in complex with CDK1, and CDK1Thr161 phosphorylation in cancer cell lines or tumors." (PMID 25268741, 2014). "Fifty eight (96.7%) low grade carcinomas showed low levels of CDK1, while 39 (79.6%) high grade carcinomas expressed elevated levels of CDK1." (PMID 25149538, 2014). "Of these 50 tumors, 40 expressed high CDK1 levels, and conversely, CDK1 expression was reduced in 13 out of 16 carcinomas with high βTrCP." (PMID 25149538, 2014). "To check this, we first analyzed the immunohistochemical expression of CDK1 and βTrCP in a tissue microarray containing 66 human carcinomas of different sites." (PMID 25149538, 2014).